SULF1 (sulfatase 1)
Diseases named in the same sentence as SULF1 in open-access papers (continued):
Sharing a sentence is not in itself a finding about the gene and the disease.
ovarian carcinoma (22 papers, 2006 to 2025). A malignant neoplasm originating from the surface ovarian epithelium. "In this study, we genotyped five putatively functional common SULF1 SNPs to investigate associations between these genetic variants and clinical outcomes in ovarian cancer patients." (PMID 21214932, 2011). "A recent study demonstrated that a predictive model based on the combination of radiomics with single nucleotide polymorphisms of Human Sulfatase 1 could predict platinum resistance in ovarian cancer treatment." (PMID 38252469, 2024). "However, it has been recently demonstrated that the loss of Sulf1 expression promotes tumorigenicity in ovarian cancer cells through regulating Bim expression." (PMID 25105093, 2014). "Downregulation of SULF1 mRNA in ovarian cancer cells, achieved via siRNA, reduces sensitivity to cisplatin-induced cytotoxicity, indicating that loss of SULF1 mRNA promotes chemoresistance." (PMID 41373732, 2025). "In ovarian cancer cell lines and primary tumors, the SULF-1 gene has been found markedly downregulated by epigenetic mechanisms." (PMID 36359323, 2022). "In breast and ovarian cancers, SULF1 exhibition of a tumor suppressive effect was relevant to its ability to attenuate FGF2, HB-EGF, and amphiregulin signaling." (PMID 28525382, 2017). "Many published studies reported that Sulf-1 is down regulated in various cancers such as ovarian cancer, breast cancer, head and neck squamous cell carcinoma and renal cell cancer." (PMID 27626699, 2016). "Recently, it was shown that Sulf1 depletion in ovarian cancer cells resulted in marked decrease in pro-apoptotic protein such as Bim, thus promoting tumor growth." (PMID 25105093, 2014). "Sulf1 has been shown to be markedly downregulated in ovarian cancer cell lines and 75% of ovarian cancer tumor tissues." (PMID 25105093, 2014). "Along these lines, it was demonstrated that genetic silencing of Sulf1 in ovarian cancer cells attenuated cisplatin induced cytotoxicity." (PMID 25105093, 2014). "Additional studies with larger sample sizes with mechanistic studies to understand biological relevance of SULF1 SNPs in the development of ovarian cancer are needed to validate the role of SULF1 SNPs in age of disease onset and prognosis of ovarian cancer." (PMID 21214932, 2011). "Loss of heterozygosity or hypermethylation of the promoter region has been suggested as potential mechanisms for SULF1 down-regulation in ovarian cancer." (PMID 21214932, 2011). "The mRNA expression of SULF1 has been reported to inhibit tumor growth and angiogenesis in breast cancer cell lines and also altered cisplatin-treatment response in ovarian cancer." (PMID 21214932, 2011). "In ovarian cancer, decreased expression of SULF1 and its correlation with decreased sensitivity to cisplatin (a standard chemotherapeutic agent) were also reported." (PMID 21214932, 2011). "Lai and colleagues have reported downregulation of Sulf-1 transcripts in human ovarian cancer and a subset of hepatocellular carcinomas." (PMID 16417632, 2006). "In striking contrast to the results in ovarian cancer, increased levels of SULF1 or SULF2 transcripts are observed in other human cancers including breast and pancreatic carcinomas." (PMID 16417632, 2006). "In a similar study with the GeCKO library in the A2780 and SKOV3 ovarian cancer cell lines, ZNF587B, TADA1, SEMA4G, POTEC and USP17L20 were identified as candidate genes; among these, loss of ZNF587B and SULF1 gene expressions were associated with cisplatin resistance." (PMID 40242936, 2025). "SULF1 expression has been reported to be decreased in various cancers, including ovarian cancer." (PMID 21214932, 2011). "Apart from the opposing roles played by Sulf1 and Sulf2 in regulating tumor growth through mobilizing heparan binding growth factors, these endosulfatases are also involved in regulating apoptotic proteins enhancing the sensitivity to chemotherapeutic agents in ovarian cancer." (PMID 25105093, 2014).
ovarian carcinoma (continued). "Several genes silenced by promoter DNA hypermethylation such as MLH1, SULF1, SFRP, TNFRSF10A, UCHL1, and CLDN4 are related to platinum resistance in ovarian cancer." (PMID 33680048, 2020). "We had previously reported that HSulf-1 (also known as Sulfatase 1, Sulf-1, KIAA1077 and Extracellular Sulfatase Sulf-1 is downregulated in a majority of ovarian cancer cell lines and tumors including serous, endometrioid and clear cell tumors of the ovary." (PMID 26378042, 2015). "Ovarian cancer cell lines and primary tumors lacking SULF1 mRNA expression showed dense DNA methylation in 12 CpG sites within exon 1A and increased histone H3 methylation around the SULF1 gene promoter, leading to transcriptional repression." (PMID 41373732, 2025). "SULF1 may regulate cell signaling by altering the sulfated state of the acetyl heparan sulfate chain, thereby affecting platinum sensitivity; in addition, knockdown of ZNF587B, a C2H2-type zinc finger protein, significantly reduced cisplatin sensitivity in ovarian cancer cells." (PMID 38084101, 2023). "However, genetic variation in SULF1 has not been explored in ovarian cancer." (PMID 21214932, 2011).
breast carcinoma (20 papers, 2007 to 2025). "High expression of SULF1 was associated with poor prognosis in advanced breast cancer brain metastasis and was positively correlated with the expression of HER2." (PMID 38590118, 2025). "Analysis of ovarian and breast cancer patients has shown that SULF-1 expression associates with a better prognosis validating in vitro data, which indicate a tumor suppressive role of this sulfatase." (PMID 36359323, 2022). "In the gene-level analysis, we found two significant genes (SLCO5A1 and SULF1, P < 0.05 after Bonferroni correction) associated with breast cancer survival." (PMID 31949161, 2020). "Clinically, it has been shown that Sulf1 expression is associated with increased disease-free and overall survival in breast cancer." (PMID 25105093, 2014). "Furthermore, SULF1 is associated with poor prognosis in the case of breast cancer." (PMID 39682235, 2024). "Considering the high expression of SULF1 in primary breast cancer and in metastatic breast cancer with ERBB2 amplification, we further investigated mutations of SULF1 in breast cancer and their relationship with ERBB2 (HER2)." (PMID 38590118, 2025). "Expression of SULF1 was higher in metastatic breast cancer with ERBB2‐amplification (HER2‐amplification) status." (PMID 38590118, 2025). "This study, through bioinformatics analysis, unveiled SULF1 as a potential target for treating breast cancer brain metastasis (BM)." (PMID 38590118, 2025). "In conclusion, using bioinformatic analysis, we propose that SULF1 can serve as a prognostic marker for poor outcomes in breast cancer brain metastasis and is a potential therapeutic target." (PMID 38590118, 2025). "In our multivariate Cox proportional hazards model, increasing levels of SULF1 increased the HR in breast cancer patients (22% increase for one standard deviation increase in gene expression), in contrast to the positive prognostic impact of TGFB2 mRNA levels." (PMID 41373732, 2025). "According to the current chemotherapy regimens for advanced breast cancer patients, we matched the expression of SULF1 with the sensitivity of first‐line drugs." (PMID 38590118, 2025). "To explore potential therapeutic drugs for breast cancer brain metastasis with high SULF1 expression, we conducted searches in two drug screening databases." (PMID 38590118, 2025). "We obtained a list of genes related to breast cancer metastasis associated with SULF1 from the GO and KEGG databases, revealing an association between the SULF1 gene and the ‘extracellular matrix’ (ECM)." (PMID 38590118, 2025). "Further experimental and clinical trials investigating the role of SULF1 in breast cancer brain metastasis should be beneficial in understanding breast cancer treatment and providing new possibilities for more treatments." (PMID 38590118, 2025). "In breast cancers under hypoxic conditions, SULF1 is downregulated by HIF-1α, promoting cancer cell migration and invasion, in aggressive breast cancer cell lines." (PMID 41373732, 2025). "SULF1 was reported to be a tumor suppressor, and to be downregulated in primary breast cancer tissue." (PMID 29507672, 2018). "Tumor suppressive effects of Sulf1 are predominantly linked to its ability to decrease FGF2, HB-EGF, amphiregulin signaling in ovarian and breast cancer cells." (PMID 25105093, 2014). "We were able to show that FXYD3 and PTX3 expression is associated with poor overall patient survival in SCC patients and LAD1, SLC7A5, SLPI, NID2, SPOCK1 and SULF1 correlated significantly with impaired pCR in breast cancer patients." (PMID 23251436, 2012). "Additionally, we analyzed the possible mechanisms of breast cancer brain metastasis and the pathways in which SULF1 was involved." (PMID 38590118, 2025). "In addition, a transcription factor vHNF has been shown to suppress Sulf1 expression in clear cell carcinoma, whereas HIF-1 alpha have been shown to suppress Sulf1 transcription in breast cancer cell lines." (PMID 25105093, 2014).
breast carcinoma (continued). "As such, the upregulation of two cell-surface PGs, glypican-1 (GPC1) and syndecan-1 (SDC1), and of the extracellular sulfatase Sulf-2, have been described in malignant breast cancer tissues whilst the downregulation of some genes including SULF1 and HS3ST2 has also been reported." (PMID 23327652, 2013). "From the upregulated genes of the EMT-core gene list, high PTX3 expression tends to poor overall survival of SCC patients (p = 0.16) and high expression of NID2 (p = 0.0091), SPOCK1 (p = 0.038) and SULF1 (p = 0.00029) significantly correlated with impaired pCR of breast cancer patients." (PMID 23251436, 2012). "Downregulation of human sulfatase-1 (SULF1), a heparin-degrading endosulfatase, observed in breast cancer cells, is shown to increase cell migration and invasion." (PMID 31013618, 2019). "Furthermore, the correlation between SULF1 expression and HER2 amplification status in breast cancer (MET500 Dataset18) was also screened." (PMID 38590118, 2025). "With regard to breast cancer, previous studies indicate an upregulation of SULF2, while SULF1 has been found to be down regulated in some breast cancer cell lines, although in our study we could only detect a small reduced relative abundance of mRNA of SULF1 in less than 10% of the cases analyzed." (PMID 23327652, 2013).
pancreatic cancer (15 papers, 2007 to 2025). "In pancreatic cancer, high SULF1 expression has been associated with later T, N, and TNM stages, higher CA19-9 levels, smaller tumor size, and poorer prognosis." (PMID 41373732, 2025). "This study identifies and validates a novel five-gene transcriptomic signature (LAMC2, TSPAN1, MYO1E, MYOF, and SULF1) as both diagnostic biomarkers and potential drug targets for pancreatic cancer." (PMID 39850570, 2024). "High SULF1 expression was associated with poor prognosis in adenocarcinoma, and silencing of this enzyme inhibited proliferation of pancreatic cancer cells." (PMID 23144729, 2012). "Pancreatic cancer (PDAC) is the only CPTAC study with both SULF1 and SULF2 protein significantly upregulated >2-fold in tumors compared with paired normal tissues." (PMID 36428645, 2022). "It has been proposed that SULF-1 as well as SULF-2 are positive regulators of pancreatic cancer development through the Wnt signaling pathway." (PMID 36359323, 2022). "Human samples of surgical resections of pancreatic cancers (n=15) showed strong staining of SULF1, which decreased in metastatic tissue samples, suggesting that complete desulfation of HSPGs occurs mainly in the process of invasion." (PMID 34249755, 2021). "The SULF2 protein is expressed in pancreatic cancer cells; both SULF1 and its homolog SULF2 have been shown to deferentially splice to regulate pancreatic tumor progression and have been proposed as both biomarkers and treatment targets." (PMID 33114263, 2020). "Taken together, heparanase, Sulf1, and Sulf2 are enzymes which appear, at least in pancreatic cancer, to be positive regulators of tumor development." (PMID 25105093, 2014). "Although several studies reported that SULF1 expression was downregulated in different types of cancer, SULF1 was upregulated in gastric and pancreatic cancers." (PMID 21214932, 2011). "Mining of public DNA microarray datasets and a quantitative PCR study establish that SULF1 transcripts are upregulated in human pancreatic cancer." (PMID 17460759, 2007). "However, the ability of Sulf1 to potentiate autocrine Wnt signaling in pancreatic cancer cells appears to be the key factor for tumors driven by this canonical signaling pathway." (PMID 25105093, 2014). "SULF1 and THBS2 have both been recently suggested as core regulators of gene co-expression networks in pancreatic cancer." (PMID 33114263, 2020). "The finding that Sulf1 and Sulf2 can promote canonical Wnt signaling, a well described cascade in PDAC, suggests their overexpression is a contributory factor in relation to the growth and tumorigenicity of these pancreatic tumor cells." (PMID 25105093, 2014).
prostate carcinoma (8 papers, 2015 to 2024). A carcinoma that arises from epithelial cells of the prostate gland. "SULF1 was demonstrated to antagonize Wnt3A-induced growth and disrupt cellular architecture in prostate cancer models." (PMID 39391236, 2024). "In cancer-stroma-macrophage triculture models, it was shown that the reduction in SULF1 stimulate the progression of bone metastasis in prostate cancer." (PMID 35453667, 2022). "At first it seemed counterintuitive that SULF1 levels are reduced in the metastatic-castrate resistant prostate cancer (mCRPC) specimens, but continue to be expressed in CAFs, as demonstrated here." (PMID 32413029, 2020). "SULF1 is present in prostatic stromal cells in the transition regions between cancer and stroma and SULF2 chromosome locus is associated to prostate cancer susceptibility regions." (PMID 25887999, 2015). "Moreover, SULF1 reduced Wnt3a-induced prostate cancer cell growth in tri-culture system consisting of prostate cancer cells, fibroblasts, and macrophages, although further investigation is warranted to determine the clinical relevance of these observations." (PMID 33050237, 2020). "Consistent with this hypothesis, data gathered in the Prostate Cancer Transcriptome Atlas, comprising over 1300 clinical specimens from 38 cohorts, show a significant reduction of SULF1 expression in metastatic castrate-resistant PCa compared to benign and primary tumors." (PMID 32413029, 2020). "Another study reported that M2 macrophages increase the transcription levels of SULF1 and HSPG2 in bone marrow fibroblasts and affect the microenvironment of prostate cancer bone metastasis." (PMID 36612128, 2022). "A heparin sulfate proteoglycan, perlecan, and its modifiers, SULF1, were abundantly present at α-SMA+ fibroblasts in prostate cancer bone metastasis sites." (PMID 33050237, 2020).
lung adenocarcinoma (7 papers, 2007 to 2025). A carcinoma that arises from the lung and is characterized by the presence of malignant glandular epithelial cells. "SULF1 mRNA expression was associated with a poor prognosis in lung adenocarcinoma." (PMID 41373732, 2025). "Furthermore, we found that high SULF1 expression was associated with a poor prognosis in lung adenocarcinoma." (PMID 21599997, 2011). "In addition, factors previously identified to be specific markers of lung adenocarcinoma were upregulated, including PROM2, CLDN3, and TJP3, as were genes proposed to have potential diagnostic or prognostic value in human cancers, including MMP9, AGR2, SULF1, NHSL1, LGR5, MUC1, and PIK3C2G." (PMID 31434729, 2019).
melanoma (6 papers, 2016 to 2026). A malignant, usually aggressive tumor composed of atypical, neoplastic melanocytes. "Functionally, SULF1 depletion impaired melanoma cell migration and invasion in vitro and reduced spontaneous metastasis in an orthotopic xenograft model." (PMID 41648528, 2026). "Future studies will be focused on investigating the TFCP2/SULF1 regulatory axis as a viable drug target in melanoma and other tumor types." (PMID 37061003, 2023). "Overall, our results, as well as clinical patient data, suggest that TFCP2 and SULF1 should be further explored as potential targets for melanoma therapy." (PMID 37061003, 2023). "Previous studies have shown that overexpression of SULF1 in melanoma inhibits cell growth and tumor growth in mice." (PMID 37061003, 2023). "To determine whether the expression of TFCP2 and/or SULF1 correlate with the survival of patients with melanoma, we analyzed clinical data from the TCGA database using the University of Alabama at Birmingham UALCAN interactive web portal." (PMID 37061003, 2023). "TFCP2-mediated repression of SULF1 may link these observations, and our data showing that knockdown of SULF1 increases melanoma cell growth correlate well with these findings." (PMID 37061003, 2023). "A375 TFCP2 knockout human melanoma cells have decreased expression of HS3ST3A1 and HS6ST2 and increased expression of SULF1 and SULF2 what allowed the authors to state TFCP2 as a novel transcriptional regulator of HS biosynthesis." (PMID 39318629, 2024). "Pharmacological targeting of TFCP2 activity similarly reduced growth factor binding and increased SULF1 expression, and the knockdown of SULF1 expression in TFCP2 mutant cells restored melanoma cell growth." (PMID 37061003, 2023). "Therefore, we knocked down TFCP2 expression using RNA interference in A375 (melanoma), HeLa (cervical adenocarcinoma), A549 (lung carcinoma), Hep3B (liver hepatocellular carcinoma), and MDA-MB-231 (triple negative breast adenocarcinoma) cells and measured FGF1 binding and SULF1 expression." (PMID 37061003, 2023). "Correspondingly, we found an increase in SULF1 expression in SKMel2, SkMel5, and UACC62 melanoma cells, with no change in SULF1 mRNA levels in SKMel28 cells." (PMID 37061003, 2023).
cervical cancer (4 papers, 2011 to 2021). A primary or metastatic malignant neoplasm involving the cervix. "In a subsequent study by the same group, genes/regions statistically significantly associated with CIN3 or cervical cancer included viral infection and cell entry genes OAS3, SULF1, and IFNG; the DNA repair genes DU, DMC, and GTF2H4; the EVER1 and EVER2 genes." (PMID 23554684, 2011). "OAS3, SULF1, DUT, and GTF2H4 SNPs were associated with HPV persistence, whereas IFNG and EVER1/EVER2 SNPs were associated with progression to cervical cancer." (PMID 23554684, 2011). "That effort identified 8 potential genes associated with cervical cancer, including the immune genes 2′,5′ oligoadenylate synthetase gene 3 (OAS3) and sulfatase 1 (SULF1), and the epidermal dysplasia verruciformis (EV)-associated EVER1 and EVER2 genes, TMC6 and TMC8." (PMID 22496757, 2012).
Colon cancer (4 papers, 2013 to 2024). "In colon tumors, for example, significant upregulation of extracellular sulfatases SULF-1/2 has been observed and may indicate general alteration of HS 6-O-sulfation patterns in colon tumors." (PMID 31620357, 2019). "Interestingly, genes that are associated with colon cancer progression (ANTXR1, EFEMP2, SULF1, TAGLN, VCAN, ZEB1 and ZEB2) were upregulated in patients co-overexpressing TAZ-AXL-CTGF." (PMID 23372686, 2013). "Colon cancer biomarkers were also differentially expressed in these two groups of patients, namely EFEMP2, a serum biomarker for early detection of colon cancer and SULF1, a protein important in colon cancer diagnosis and whose serum level is elevated in patients with colon adenomas." (PMID 23372686, 2013).
colorectal cancer (4 papers, 2016 to 2025). A primary or metastatic malignant neoplasm that affects the colon or rectum. "Underproduction of butyrate in patients with colorectal carcinoma can increase SULF1 and CAFs." (PMID 40677714, 2025).